SLC23A3 (solute carrier family 23 member 3)
Description:
Acts as a sodium-dependent hypoxanthine transporter. May show xanthine-hypoxanthine exchange activity.
Synonyms: E2BP3; SVCT3; FLJ31168; Yspl1
Tractability: Antibody: UniProt predicts a signal peptide or a membrane-spanning region.
Gene: Protein-coding gene on chromosome 2 (219,161,465 to 219,170,095, reverse strand). Ensembl gene ENSG00000213901.
Subcellular location: Membrane
Subcellular location (Human Protein Atlas): Nucleoplasm; Cell Junctions
Gene Ontology:
Molecular function: transmembrane transporter activity
Biological process: hypoxanthine transport; transmembrane transport
Cellular component: membrane
Genetic constraint (gnomAD): Loss-of-function variants: 40 observed, 65.92 expected, observed/expected ratio (o/e) 0.61, 90% interval 0.47 to 0.79. The upper end of that interval is the gene's LOEUF score, 0.79, which puts it in group 3 of 6, group 1 being the genes least tolerant of losing a copy. Missense variants: 644 observed, 757.88 expected, observed/expected ratio (o/e) 0.85, 90% interval 0.8 to 0.91. Synonymous variants: 281 observed, 319.06 expected, observed/expected ratio (o/e) 0.88, 90% interval 0.8 to 0.97.
Homologues: Orthologues: chimpanzee SLC23A3 (99% identical), macaque SLC23A3 (97% identical), pig SLC23A3 (81% identical), mouse Slc23a3 (78% identical), rat Slc23a3 (77% identical), guinea pig SLC23A3 (74% identical), tropical clawed frog slc23a3 (39% identical), Caenorhabditis elegans C51E3.6 (22% identical), Caenorhabditis elegans R11E3.2 (21% identical), Caenorhabditis elegans T07G12.2 (20% identical), zebrafish slc23a3 (20% identical), Caenorhabditis elegans T07G12.5 (20% identical), and 2 more. Paralogues in human: SLC23A1 (28% identical), SLC23A2 (28% identical).
Diseases named in the same sentence as SLC23A3 in open-access papers:
SLC23A3 is named in the same sentence as 3 diseases in open-access papers, as found by Europe PMC text mining. Sharing a sentence is not in itself a finding about the gene and the disease. The quoted sentences say what the papers report.
schizophrenia (1 paper, 2017). A major psychotic disorder characterized by abnormalities in the perception or expression of reality. "Another interesting signal in this region is at the SNP rs613539 which corresponds to SLC23A3 gene, which has been claimed to be a candidate for schizophrenia susceptibility in the Japanese population." (PMID 28423003, 2017). "Worth mentioning is the SLC23A3 gene that has been associated to schizophrenia susceptibility in the Japanese population and that we found to be significant both in ASN-YRI and CEU-YRI comparisons." (PMID 28423003, 2017).
type 2 diabetes (1 paper, 2023). "In the case of type 2 diabetes, of the 11 genomic regions association with ascorbate plasma concentration in 80,983 cases and 842,909 noncases, the strongest signal was found with SLC23A1, the vitamin C transporter SVCT1, with a significant signal also with SLC23A3, the orphan transporter SVCT3." (PMID 36766828, 2023).
SLC23A3 also shares sentences with these, for which no sentence is quoted: hematological diseases (1 paper).